PPARG (peroxisome proliferator activated receptor gamma)
Diseases named in the same sentence as PPARG in open-access papers (continued):
Sharing a sentence is not in itself a finding about the gene and the disease.
tumor (continued). "FZD9 is required in lung epithelial cells for iloprost to activate peroxisome proliferator activated receptor gamma (PPARG) and related anti-tumor signaling." (PMID 35149732, 2022). "The administration of this natural product inhibited tumor growth by downregulating PPARα, PPARγ, FABP1, FABP4, and FABP5." (PMID 36296934, 2022). "In melanoma, tumor cells activate WNT5a/β-catenin-PPARγ signaling, which in turn upregulates the expression of carnitine palmitoyltransferase-1a (CPT1A) to promote FAO." (PMID 36244976, 2022). "The immunohistochemistry assay revealed that the PPARγ expression in tumor tissue with the BI injection group was increased (control vs. BI: 5.06 ± 0.90 vs. 8.28 ± 1.02, p < 0.05)." (PMID 35341213, 2022). "The quantifiable description of PPARγ expression pattern beside mechanistic in-vitro evidence will provide insights into the involvement of this mediator in tumor pathogenesis." (PMID 35922782, 2022). "Artemether can substantially upregulate the expression of PPARγ, suggesting that it can activate abnormally accumulated PPARγ in tumor tissue." (PMID 35911149, 2022). "Compared with previous findings, we reported for the first time that circRFWD3 exerts its functions in promoting tumor metastasis by harboring miR-27a/b to enhance the expression of PPARγ, which is the downstream target of miR-27a/b." (PMID 35690612, 2022). "A bidirectional interaction between the FABP4 and PPARγ pathways has been identified to potentially drive the aggressive behavior of tumor cells in bone." (PMID 36760798, 2022). "Src inhibition impairs LD formation by activating PPARγ-induced FABP4 expression and elevating reactive oxygen species (ROS) production, suggesting the critical role in Src/PPARγ/FABP4 axis in tumor proliferation." (PMID 35899119, 2022). "Cheng and co-workers demonstrated that GW9662 can inhibit PPARγ function, thus significantly impairing bladder cell proliferation in vitro, and decreasing tumor growth in vivo." (PMID 35625629, 2022). "PPARγ is a regulator of lipid and glucose homeostasis and can upregulate tumor suppressor genes, such as BRCA1 and PTEN." (PMID 35625629, 2022). "Most in vivo studies using different PPARγ agonists observed an inhibition of tumor angiogenesis upon PPARγ activation." (PMID 35954274, 2022). "The impact of PPARγ on cancers is complex and bidirectional, PPARγ acts as a tumor promoter by induction of lipogenic gene ACLY, MIG12, FASN, and NR1F1, stem cell-related gene KLF4, ALDH and upregulation Nox1 ROS, and VEGF." (PMID 36587194, 2022). "Consistently, both PPARγ protein and gene expression was considerably effective in predicting tumor recurrence." (PMID 35922782, 2022). "Similar to activation by FZD9, PPARG is also activated by prostacyclin in lung epithelial cells, leading to anti-tumor signaling." (PMID 35149732, 2022). "Many genes and factors regulated by PPARγ are also intimately correlated with tumor formation and development." (PMID 35911149, 2022). "Pro-anakoinotic therapy with PPARγ agonists may attenuate Wnt signaling as both pathways can be regarded antagonists, thereby concertedly inducing differentiation, enhancing immune response, reducing tumor-associated inflammation, angiogenesis and cell proliferation." (PMID 35814409, 2022). "Cox univariate analysis indicated that patients with tumors coexpressing RXRα and PPARγ in the cytoplasm of tumor cells have a decreased 5 y OS rate." (PMID 35406808, 2022). "These genes have been associated with tumour suppression (BRCA1 and FAT1), DNA repair (POLE), morphogenesis (HOXD11), epigenetic regulation (WHSC1), lipid metabolism (PPARG) and red blood cell development (GATA1)." (PMID 36131292, 2022). "Although a large body of evidence suggests that PPARγ functions as a tumor suppressor, the role of PPARγ in tumorigenesis remains controversial." (PMID 35954274, 2022).
tumor (continued). "Research on PPARγ in tumor cells has yielded divergent results; in some studies it acted as a tumor suppressor, but others reported growth-promoting effects." (PMID 35079875, 2022). "Blocking CD200 inhibition of MAPK or PPARγ signaling restored NK cell survival and tumor cell killing, with relevance to many cancer types." (PMID 36074574, 2022). "A similar pattern of PPARγ expression level was observed in Ewing Sarcoma tumors compared to normal tissue that showed a significant elevation in tumor tissues (0.23 ± 0.12) compared to normal bone tissues (0.12 ± 0.07) (P = < 0.0001)." (PMID 35922782, 2022). "According to RNA-seq data, PPARγ downstream genes were clearly downregulated, indicating that the tumor-suppressing effect of FH535 is mainly mediated by PPARγ." (PMID 35974387, 2022). "Treatment of rosiglitazone, an agonist of PPARγ, impeded tumor progression via inhibiting GPR132 expression on TAMs." (PMID 36244976, 2022). "Immunohistochemical staining of representative samples verified the predominant expression of PPARγ (pS112) and PR by cancer cells in cold tumor samples." (PMID 36139700, 2022). "Implantation of these cells into the lungs of nude rats was shown to exert inhibitory effects on tumor growth and metastasis, suggesting the inhibitory effects of PPARγ on lung tumorigenesis involve selective inhibition of invasive metastasis." (PMID 35631448, 2022). "PPZ023 (1-(2-(ethylthio)benzyl)-4-(2-methoxyphenyl)piperazine), a novel peroxisome proliferator-activated receptor gamma (PPARγ) ligand candidate, has a powerful anticancer effect against tumor growth." (PMID 36032078, 2022). "pIκB, IκB, pIκB/IκB ratio, COX2, PPARγ, IL-4R and IFNγ protein levels were studied in both tumor and non-tumor adjacent tissues in all stages from CRC patients." (PMID 36139645, 2022). "Previous studies have shown that PPARγ expression in tumor tissues of NSCLC is higher than that in surrounding normal tissues." (PMID 35911149, 2022). "While multiple lines of evidence highlighted the tumor suppressive role of PPARγ in regulating cancer cell growth and PPARγ agonists induced different types of programmed cell death pathways in cancer cells." (PMID 35922782, 2022). "PPARγ act as a tumor suppressor by inducing apoptosis through the upregulation of PTEN, suppression of NF-κB, and many other signaling pathways." (PMID 36587194, 2022). "The correlation of PPARγ expression level with patients’ clinic-pathological features, also the value of the variables in predicting PPARγ expression level in tumors and the value of PPARγ to discriminate tumor subtypes were assessed." (PMID 35922782, 2022). "Exposure of tumor bearing mice to γ-irradiation in combination with thiophene derivative or cisplatin significantly augmented the effect of thiophene derivative on PPARγ." (PMID 36326938, 2022). "The retinoic acid-producing enzyme aldehyde dehydrogenase 1a1 acts as a tumor suppressor in splenic B-cell subpopulations by regulating retinoic acid receptor alpha, zinc finger protein Zfp423, and PPARγ." (PMID 35954274, 2022). "The cleavage of PPARγ by caspase-1 has been shown to enhance tumor promotion through the induction of TAMs." (PMID 35954274, 2022).
tumor (continued). "In conclusion, although PPARα and PPARγ seem to decrease tumor angiogenesis, caution should be taken regarding the therapeutical use of any PPAR agonist in the setting of susceptibility to cancer." (PMID 35954274, 2022). "Yet, no clinical trials have proven the combinatory use of KRAS inhibitors with parallel tumor tissue editing by PPARγ agonists." (PMID 35814409, 2022). "PPARγ has been shown to drive invasive behavior of tumor cells by increasing cell motility in other cancer types." (PMID 34984327, 2022). "PPARγ/RXRα signal has been proven to inhibit the growth of cancer cells and reduce tumor invasiveness in a variety of cancers." (PMID 36286423, 2022). "CBD also led to an upregulation of COX-2 and PPARγ in tumour tissue in A549-xenografted nude mice and to tumour regression, which was reversed by a PPARγ antagonist." (PMID 35277658, 2022). "Mechanically, DHA-PC and EPA-PC activated PPARγ, and PPARγ directly regulated the activity of tumor-related factors to achieve the antitumor effects." (PMID 36364935, 2022). "A recent study further demonstrated that PPARγ agonists can enhance a pro-tumorigenic secretome in cancer cells, leading to increased tumor angiogenesis and progression." (PMID 35954274, 2022). "Conversely, some literature has reported that PPARγ plays a key role in tumorigenesis as a tumor suppressor." (PMID 36359869, 2022). "PPARγ further enhances the anti-tumor efficacy of iNKT cells by assuring cholesterol synthesis and IFN-γ production in tumor-infiltrating iNKT cells." (PMID 35954274, 2022). "Lately, there has been growing attention to exploring the ability of PPARγ in inflammation, lipid metabolism, and tumor growth, especially in cancer cachexia." (PMID 34093209, 2021). "A similar effect was observed in the OE clones, where EV7 developed a few small tumours, yet once again all of these were PPARG positive." (PMID 33654198, 2021). "Current consensus depicts that PPARγ exhibits a pro-tumorigenic effect in immune cells by promoting alternative activation, which contradicts its anticancer properties in tumor epithelium and CAFs." (PMID 33946986, 2021). "telmisartan can modulate the ERK1/2, TAK1 and NF-κB signaling axis, such as agonist of PPARγ, exerting antitumor effects, and increasing tumor sensitivity to sorafenib." (PMID 34361064, 2021). "In this study, we thoroughly evaluated the prognosis of PPARG in BRCA and its specific characteristics, including DNA methylation, tumor immune microenvironment, and tumor mutation burden." (PMID 34567087, 2021). "Taken together, PPARγ acts as a master immuno-metabolic switch in immune cells that govern their fate and tumor-supporting role." (PMID 33946986, 2021). "Clinical trials repurposing peroxisome proliferator-activated receptor-gamma (PPARγ) agonists as anticancer agents have exhibited lackluster efficacy across a variety of tumor types." (PMID 34580286, 2021). "Otherwise, for its crucial role in cellular energy homeostasis, immune cells also require PPARγ activation to meet energy demands and regulate lipid metabolism and cell fate, which is involved in tumour immune microenvironment." (PMID 33797188, 2021). "We then analyzed TCGA dataset and found that the mRNA expression of PPARγ was correlated with overall survival and tumor stage." (PMID 35186942, 2021). "Studies have shown that PPARγ agonists can inhibit the growth of a variety of cancer cells in vitro, and in combination with other chemotherapeutic drugs, can enhance the anti-tumor effect of the drugs." (PMID 37073266, 2021). "Stimulation of PPARγ can inhibit neoplastic processes by suppressing tumor cell replication and decreased survival of tumor cells." (PMID 34768791, 2021). "PLA2G16 was first recognized as a type II tumor suppressor gene and was identified as a PPARγ target gene, expressed specifically in adipose tissue." (PMID 33643070, 2021).
tumor (continued). "In contrast to the tumor-supporting properties of CAFs overexpressing PPARγ, pharmacologic PPARγ activation in tumor epithelium confers anticancer effects by reducing tumor proliferation and neovascularization." (PMID 33946986, 2021). "In summary, we can conclude that the expression level of PPARG in the normal group was significantly higher than that in the tumor group." (PMID 34567087, 2021). "Lastly, by inducible and conditional deletion of PPARγ in ILCs using PPARgfl/flId2CreERT2 mice and a heterotypic tumor model, we show significant reduction of cancer development and progression in vivo." (PMID 33953160, 2021). "Immunohistochemistry (IHC) analysis on those KO tumours that did develop showed that all expressed PPARG." (PMID 33654198, 2021). "The findings in the three HCC of our cohort (i.e., two cases with PAX8/PPARγ rearrangements and one wild-type tumour) were quite unexpected." (PMID 32638211, 2021). "Given the fact that PPARγ has been reported to act as a tumor suppressor in several cancers and PPARγ silencing increased the expression of C-myc, NF-κB, CyclinD1, cyclin E, MMP2, and MMP9 in BC cells." (PMID 33777130, 2021). "Peroxisome proliferator-activated receptor-γ (PPARγ) is a ligand-activated nuclear hormone receptor that functions as transcription factor and is over-expressed in many tumor types, including BC." (PMID 33670444, 2021). "Studies have revealed that PPARG acts as a tumor suppressor and plays an important role in tumorigenesis." (PMID 34023860, 2021). "PGC1α suppresses HCC cell metastasis by inhibiting the Warburg effect through regulation of the WNT/β-catenin/PDK1 axis, concluding that the tumor suppressor activity of PGC1α depends on PPARγ." (PMID 34361064, 2021). "PPARγ functions as a tumor suppressor, it promotes apoptosis and inhibits cancer cell proliferation, angiogenesis, and tumor microenvironment inflammation." (PMID 34199293, 2021). "In both cases, the molecular mechanisms have been identified in the regulation of their promoter genes, highlighting that PPARγ functions as a gene modulator and determinant of tumor cell fate." (PMID 34067944, 2021). "IHC analysis demonstrated, elevated Ki67 expression, and PPARG in all tumours derived from the OE clones as compared to EV7." (PMID 33654198, 2021). "The findings from the TIMER database expressed that the mRNA expression level of PPARG in the normal group was significantly higher than that in the tumor group." (PMID 34567087, 2021). "Five out of six mice implanted with clone OE19, the clone expressing the highest level of PPARG, generated tumours." (PMID 33654198, 2021). "In some tumor entities, a positive prognostic influence of nuclear PPARγ expression on the survival of tumor patients has already been identified, but a difference between expression localization and relation to different patient outcome was not described." (PMID 33802010, 2021). "Clones OE12 and OE18, expressing intermediate levels of PPARG, produced tumours ranging in size between that of the EV7 and OE19 clones." (PMID 33654198, 2021). "Although PPARγ signalling has been demonstrated to have an anti-tumor activity by supporting differentiation and suppressing proliferation, ML patients with relatively higher expression of PPARγ had reduced recurrence- or metastasis-free survival." (PMID 33669307, 2021). "As the physiological cues in a TME are different from a normal condition, the true nature of PPARγ in cancer angiogenesis and tumor epithelium-endothelium crosstalk requires further investigation." (PMID 33946986, 2021). "In our study, the results of the TARGET dataset analysis revealed significant differences in PPARG expression between normal and tumor tissues, and western blot analysis and qRT-PCR results in RD cell lines confirmed these findings." (PMID 35187064, 2021).
tumor (continued). "Three tumor-associated genes, zinc finger and BTB domain-containing 16 (ZBTB16), peroxisome proliferator activated receptor gamma (PPARG), and transforming growth factor beta receptor 2 (TGFBR2), were downregulated with copy number variation (CNV) loss." (PMID 33414372, 2021). "The outcomes from Western blot analysis and UALCAN analysis exhibited that PPARG was under-expressed in the tumor group." (PMID 34567087, 2021). "On the one hand, TIMER, TCGA, GEO, and UALCAN displayed the lower mRNA expression of PPARG in tumor tissues than normal tissues." (PMID 34567087, 2021). "This would suggest that the tumour environment exerts a selective pressure on the tumour cells favouring those that express PPARG." (PMID 33654198, 2021). "Phosphatase and tensin homolog deleted on chromosome 10 (PTEN) is the downstream target of PPARγ and also a key tumor suppressor." (PMID 37073266, 2021). "Further validation of PPARG’s effect on this pathway was established through immunoblot of tumour lysates probing for PPARG, AKT3, PGC1α, CRM1 and VDAC1." (PMID 33654198, 2021). "Secondly, the DNA methylation level of PPARG was significantly higher in the tumor group as compared to the normal group." (PMID 34567087, 2021). "In the integrated genomic and transcriptome analyses, the tumor-associated genes ZBTB16, PPARG, and TGFBR2 were found to be significantly downregulated with simultaneous CNV loss." (PMID 33414372, 2021). "The Kaplan-Meier curve showed a significantly worse disease-free survival for patients with a PPARγ expression ≥ 2 in cytoplasm of the tumor tissue than for those whose IRS value is below 2 (* p = 0.036)." (PMID 33802010, 2021). "The results revealed that PPARγ expression level was upregulated in cancer tissues compared to that in the corresponding adjacent non-tumor tissues." (PMID 35186942, 2021). "Treatment with T0070907 significantly reduced both tumor volume and weight, suggesting a possible therapeutic use of PPARγ inhibitors in CRC patients." (PMID 33953160, 2021). "FASN, a downstream effector of PPARG, was elevated in OE orthotopic tumour samples, suggesting a metabolic effect of PPARG." (PMID 33654198, 2021). "As the most important partner of PPARγ, numerous studies have declared that the tumor‐suppressive effects of PPARγ are exerted through upregulation of PTEN, which gained its reputation due to the involvement in the PI3K signaling axis." (PMID 34549887, 2021). "Treatment with PPARγ agonist and radiotherapy enhanced the effectiveness of tumor control and dampened metastasis." (PMID 33467433, 2021). "It was found that an inverse relationship exists between 15-LOX-2 and PPARγ expression levels in normal vs tumour cells, suggestive of the occurrence of a feedback mechanism regulating the expression levels of these proteins." (PMID 33799988, 2021). "At best, the overall conclusion from these studies is that the context, e.g., specific tumor type, tumor stage, and tumor microenvironment, determines the exact role and function of PPARγ in human cancer." (PMID 33716977, 2021). "Recent studies confirmed that PPARG activation facilitates the anti-tumor effect of 6-iodolactone and hesperetin." (PMID 34567087, 2021). "In short, PPARγ regulates key genes and cellular events in CAFs to accomplish the metabolic coupling of tumor stroma and epithelium, essentially transforming CAFs into a powerhouse that constantly generates energetic biomolecules to support tumor growth." (PMID 33946986, 2021). "Many eicosanoids are also packaged in these exosomes to achieve paracrine stimulation of PPARγ and augment the inhibitory effect on tumor EMT." (PMID 33946986, 2021). "PPARγ hampered tumor development and progression, and controlled the tumor microenvironment, ameliorating tumor growth and metastasis." (PMID 33467433, 2021). "PDAC patients with high PPARγ expression exhibited advanced tumor stages and poor prognosis compared to those with low PPARγ expression." (PMID 35186942, 2021).